ANXA1 (annexin A1)
Diseases named in the same sentence as ANXA1 in open-access papers (continued):
Sharing a sentence is not in itself a finding about the gene and the disease.
lung carcinoma (continued). "In conclusion, our study showed that ANXA1 is a candidate for target therapy toward NSCLC and targeting ANXA1 may enhance the effects of EGFR-TKI in lung cancer cells with EGFR mutations." (PMID 34439260, 2021). "Since the knockdown of ANXA1 is associated with the decreased growth, invasion and migration of lung cancer cells, ANXA1 may play the role of a tumor promoter in lung cancer cells." (PMID 34439260, 2021). "In addition, increased serum annexin A1 was significantly associated with pathologic grade and clinical stage of lung cancer patients." (PMID 27071553, 2016). "The sensitivity, specificity, positive predictivity, and diagnostic coincidence rate of the ability of Hsp90-beta and annexin A1 to predict lung cancer were relatively high (above of 80%), which indicates the differential diagnostic value of Hsp90-beta and annexin A1 levels for lung cancer." (PMID 22929401, 2012). "In lung cancer, up-regulation of HSP90β is associated with the worst prognosis and poor survival; therefore, it has been proposed as a possible risk biomarker along with annexin A1; even with lung adenocarcinoma, increased levels of HSP90β have been associated to poor survival and metastasis." (PMID 34449539, 2021). "Therefore, ANXA1 may be an attractive target for lung cancer therapy and to enhance the treatment effects of Osimertinib on lung cancer cells with EGFR mutations." (PMID 34439260, 2021). "In addition, we performed a diagnostic test to investigate if Hsp90-beta and annexin A1 could function as indices for the pathological diagnosis in lung cancer." (PMID 22929401, 2012). "These included annexin A1(ANXA1) and annexin A2 (ANXA2), both known to be associated with lung cancer." (PMID 38539567, 2024). "ANXA1 expression was observed in all cancer cell lines assessed except for COR-L23 lung cancer cells." (PMID 38200229, 2024). "We demonstrated that in ANXA1-expressing breast, ovarian, pancreatic, colorectal and lung cancer cell lines, MDX-124 treatment suppressed cell proliferation." (PMID 38200229, 2024). "The group also observed that lung cancer with a high serum level of Annexin A1 is more likely to show an aggressive phenotype, i.e., poorly differentiated to undifferentiated lung cancer and lymphatic metastasis." (PMID 38893148, 2024). "For instance, ANXA1 is overexpressed in melanoma, hepatocellular carcinoma, gastric cancer, and lung cancer, while its expression is diminished in prostate and esophageal cancers." (PMID 39640883, 2024). "MDX-124, a humanized anti-ANXA1 monoclonal antibody, has been shown to suppress cell proliferation significantly in ANXA1-expressing breast, ovarian, pancreatic, colon, and lung cancer cell lines (p < 0.013)." (PMID 38893148, 2024). "A large number of studies have also demonstrated that, in addition to lung cancer, ANXA1 expression is upregulated in a variety of cancers, including hepatocellular carcinoma, colorectal cancer, pancreatic cancer, melanoma, and endometrial cancers." (PMID 36936694, 2023). "Upregulation of ANXA1 has been observed in lung cancer, pancreatic cancer, colorectal cancer, and melanomas, and has a notable correlation with advanced stages and unfavorable prognosis." (PMID 34991599, 2022). "S100-A8, thymidine phosphorylase, annexin A2, transglutaminase 2, and annexin A1 were lung cancer individuals’ most renowned over-expressed proteins." (PMID 36552956, 2022). "For example, the prognosis of lung cancer patients with a high ANXA1 expression is poor, and the growth of lung cancer cells is reduced by downregulating ANXA1 using small interference RNA (siRNA)." (PMID 35711921, 2022). "After ANXA1 knockdown, a significantly decreased growth was observed in the lung cancer cells studied." (PMID 34439260, 2021). "Further studies showed that an increased cleaved PARP was noted in ANXA1 knockdown with Osimertinib-treated lung cancer cells." (PMID 34439260, 2021).
lung carcinoma (continued). "A decreased phosphorylation of EGFR (Tyr1068) and the down-stream Akt (Ser473) pathway was noted in ANXA1 knockdown with Osimertinib treatment H1975 and H1650 lung cancer cells." (PMID 34439260, 2021). "In this study, we focused on the association of ANXA1 and chemosensitivity to Osimertinib in NSCLC lung cancer cells with EGFR mutations." (PMID 34439260, 2021). "Our study results also showed an increased inhibitory effect on the growth of lung cancer cells of Osimertinib in ANXA1 knockdown H1975 and H1650 lung cancer cells." (PMID 34439260, 2021). "A cohort of 197 lung cancer patient samples was collected in order to study the prevalence and prognostic value of ANXA1 protein expression among lung cancer patients." (PMID 33959206, 2021). "The trans-well invasion assay and wound healing assay were performed to study the effect of ANXA1 knockdown and Osimertinib on the ability for invasion and metastasis in lung cancer cells." (PMID 34439260, 2021). "An increased apoptotic cell was observed in ANXA1 knockdown with Osimertinib treatment lung cancer cells." (PMID 34439260, 2021). "In this study, we focused on the association of ANXA1 and chemosensitivity with a third generation epidermal growth factor receptor-tyrosine kinase inhibitor (EGFR-TKI), Osimertinib, in lung cancer cells with EGFR mutations." (PMID 34439260, 2021). "The role of Annexin A1 (ANXA1) in tumorigenesis and cancer progression in general and especially in lung cancer remains to be controversial and seems to be highly tissue specific and inconsistent among tumor initiation, progression, and metastasis." (PMID 33959206, 2021). "A decreased phosphorylation of HER2 was observed in H1975 and H1650 lung cancer cells after the knockdown of ANXA1 and Osimertinib treatment." (PMID 34439260, 2021). "The expression of ANXA1 was downregulated by ANXA1 siRNA in A549, H1975 and H1650 lung cancer cells." (PMID 34439260, 2021). "A mice xenograft lung cancer model was established in our study and showed that ANXA1 siRNA enhanced the effects of Osimertinib in vivo." (PMID 34439260, 2021). "In our study, the knockdown of ANXA1 also increased chemosensitivity to Osimertinib in T790M positive lung cancer cells expression stably expressing L858R + C797S EGFR mutations (H1975C797S)." (PMID 34439260, 2021). "In the anchorage-independent soft agar colony formation assay, an increased growth inhibition of Osimertinib was also observed in the ANXA1 knockdown H1975 and H1650 lung cancer cells." (PMID 34439260, 2021). "Cisplatin-resistant lung cancer A549 cells have a twofold higher expression of Anxa1 localized to both the cell surface and cytoplasm, and Anxa1 knockdown increases sensitivity to cisplatin treatment." (PMID 33446132, 2021). "ANXA1 is also known as lipocortin or P35, highly expressed in lung cancer, has been shown to attenuate metastasis in breast and prostate-derived cancer-associated fibroblasts." (PMID 33670440, 2021). "Knockout of ANXA1 expression inhibited the proliferation, migration, and invasion of lung carcinoma cells, while the expression level of ITGA3 can be used as a diagnostic and prognostic marker for several malignant tumors." (PMID 34350210, 2021). "The downregulation of ANXA1 with small interference RNA (siRNA) decreased the growth of lung cancer cells." (PMID 34439260, 2021). "A siRNA knockdown study was performed to observe the effect of ANXA1 on lung cancer cells with an overexpression of ANXA1." (PMID 34439260, 2021). "In the anchorage-dependent colony formation assay, an increased growth inhibition of Osimertinib was also observed in the ANXA1 knockdown H1975 and H1650 lung cancer cells." (PMID 34439260, 2021). "An increased growth (H1975) and decreased chemosensitivity to Osimertinib were observed in the ectopic ANXA1 overexpressed H1975 and H1650 lung cancer cells." (PMID 34439260, 2021).
lung carcinoma (continued). "In the invasion assay, an increased invasion inhibition of Osimertinib was also observed in the ANXA1 knockdown H1975 and H1650 lung cancer cells." (PMID 34439260, 2021). "In the wound healing assay, the migration of H1975 lung cancer cells was significantly inhibited in the Osimertinib treatment and ANXA1 knockdown group." (PMID 34439260, 2021). "In our study, a decreased HER2 phosphorylation was observed in H1975 and H1650 lung cancer cells after the knockdown of ANXA1 and Osimertinib treatment." (PMID 34439260, 2021). "In H1975 and H1650 lung cancer cells with EGFR mutations, the combination treatment of ANXA1 siRNA and Osimertinib resulted in significantly decreased survival cells compared to the Osimertinib group." (PMID 34439260, 2021). "The knockdown of ANXA1 also increased the chemosensitivity to Osimertinib in the H1975 C797S lung cancer cells." (PMID 34439260, 2021). "Even though several scholars have identified a significant increase of ANXA1 expression in different types of lung cancer, few have analyzed its impact on patients' survival." (PMID 33959206, 2021). "The first study linking ANXA1 to cancer was documented in lung cancer, in which ANXA1 exhibited inhibitory effects on A549 cell growth and leukocyte migration." (PMID 33531975, 2021). "High abundance of ANXA1 was identified in patients with lung cancer while knockdown of ANXA1 can inhibit the proliferation, migration and invasion of NSCLC, especially in A549 cell line." (PMID 32351780, 2020). "Elevated levels of ANXA1 have been detected in lung cancer, colorectal cancer, hepatocellular carcinoma, pancreatic cancer and in melanomas." (PMID 29614751, 2018). "Increased levels of annexin A1 are also observed in bronchoalveolar lavage fluid and correlated with lymphatic invasion and malignant progression of lung cancer." (PMID 30157864, 2018). "Previous work from in vitro cultured cells suggested that ANXA1 can inhibit the growth and proliferation of A549 lung cancer cells and prostate cancer cell lines." (PMID 28414743, 2017). "We demonstrated that Hsp90-beta and annexin A1 were upregulated in lung cancer, and the upregulation of these molecules in lung cancer was associated with poor post-surgical survival time and malignant tendency of lung cancer patients." (PMID 22929401, 2012). "The expressions of Hsp90-beta and annexin A1 in lung cancer clinical specimens were evaluated to determine the epidemiologic features of Hsp90-beta and annexin A1 as well as their clinicopathological significance in lung cancer." (PMID 22929401, 2012). "The lung cancer patients with high expressions of Hsp90-beta and annexin A1 exhibited a poorer disease-free survival than those with low expressions of Hsp90-beta and annexin A1." (PMID 22929401, 2012). "Hsp90-beta and annexin A1 were highly expressed in 57 (59.4%) and 44 (45.8%) of the 96 lung cancer tissues, respectively, whereas both were lowly expressed in three (6.5%) and seven (15.2%) of the 46 normal lung tissues." (PMID 22929401, 2012). "High expression levels of Hsp90-beta and annexin A1 were found in poorly differentiated lung cancer tissues (80.8% and 84.6%, respectively) compared with well-differentiated tissues (22.7% and 31.8%, respectively) (p < 0.0005)." (PMID 22929401, 2012). "The RR of Hsp90-beta and annexin A1 mRNA expression for lung cancer was higher than their proteins, with RR values of 16.25× and 13.33×, respectively." (PMID 22929401, 2012). "The protein expression levels of Hsp90-beta and annexin A1 were determined by IHC in a series of 96 specimens of lung cancer tissues and a series of 46 specimens of normal tissues." (PMID 22929401, 2012). "The expression levels of Hsp90-beta and annexin A1 in lung cancer cases of T3 to T4 were 85.7% (24/28) and 71.4% (20/28), which is higher than what was observed in lung cancer cases of T1 to T2, respectively (p = 0.001)." (PMID 22929401, 2012).
lung carcinoma (continued). "An upregulated mRNA expression of Hsp90-beta and annexin A1 was found in the lung cancer tissues (p = 0.006; p = 0.002)." (PMID 22929401, 2012). "We examined the cultured human lung cancer cell lines for the expressions of Hsp90-beta and annexin A1." (PMID 22929401, 2012). "Our results showed that Hsp90-beta and annexin A1 exhibited a high expression in all histological types of lung cancer, particularly in poorly differentiated lung cancer." (PMID 22929401, 2012). "High mRNA expression levels of Hsp90-beta and annexin A1 were observed in ten (41.7%) and eight (33.3%) of the 24 lung cancer tissues, whereas both markers were lowly expressed in two (8.3%) and three (12.5%) of the 24 normal lung tissues, respectively." (PMID 22929401, 2012). "Among these processes, Hsp90-beta and annexin A1 were remarkably upregulated in the lung cancer cell lines." (PMID 22929401, 2012). "The upregulation of Hsp90-beta and annexin A1 in the lung cancer tissues and the down regulation in the normal lung tissues were observed (p < 0.0005; p = 0.001)." (PMID 22929401, 2012). "The expressions of Hsp90-beta and annexin A1 in lung cancer and normal lung specimens were examined, and the relationships with respect to the clinico-pathological features and patient survival in lung cancer were analyzed." (PMID 22929401, 2012). "Previous studies have shown that annexin A1 antibody has been found in the serum of patients with lung cancer." (PMID 18637184, 2008). "Moreover, ANXA1 serum values are significantly higher in lung cancer patients with brain metastases compared to lung cancer patients without brain metastases, suggesting its potential value in metastasis detection." (PMID 41283264, 2025). "In contrast, an increased ANXA1 serum value has been reported in melanoma and lung cancer patients." (PMID 41283264, 2025). "Similar to a previous study, our study further confirmed that ANXA1 is overexpressed in lung cancer cells with or without EGFR mutations." (PMID 34439260, 2021). "We examined the expression of ANXA1 in NSCLC lung cancer cells using Western blot analysis." (PMID 34439260, 2021). "The overexpression of ANXA1 was observed in the lung cancer cells studied." (PMID 34439260, 2021). "Since HER2 amplification is the second common cause of acquired resistance to Osimertinib in T790M positive lung cancer, targeting ANXA1 may help to overcome acquired resistance through the inhibition of HER2 phosphorylation." (PMID 34439260, 2021). "ANXA1 has been reported to promote the development of tumorigenesis in lung cancer cells." (PMID 34439260, 2021). "Specifically, this effect of Cmpd17b may be independent of diabetes as it has been reported that upregulation of the endogenous FPR agonist, Annexin A1, reduces Ptgs2 expression in lung cancer cells." (PMID 32085666, 2020). "Lung cancer tissues exhibited higher expression of annexin A1 than normal tissues." (PMID 27071553, 2016). "For example, ANXA1 was investigated as a potential serum biomarker for lung cancer." (PMID 27071553, 2016). "Thus, we can infer that high expressions of Hsp90-beta and annexin A1 can potentially promote lung cancer development." (PMID 22929401, 2012). "More importantly, the risk ratio analysis result indicates that the upregulation of Hsp90-beta and annexin A1 might be an unfavorable factor in lung cancer." (PMID 22929401, 2012). "A detailed understanding of the function and significance of Hsp90-beta and annexin A1 is advantageous to elucidate further the biological mechanisms of lung cancer and aid in the design of preventive treatment because lung cancer is a highly malignant tumor in the respiratory system." (PMID 22929401, 2012).
lung carcinoma (continued). "In addition, lung cancer with high levels of Hsp90-beta and annexin A1 are more likely to show an aggressive phenotype that is exemplified by a large tumor size and lymphatic metastasis." (PMID 22929401, 2012). "Metastasis and malignant invasion are the critical factors in the progression of lung cancer, and an alteration in the expressions of Hsp90-beta and annexin A1 is highly involved in tumor cell lymph node invasion, larger tumor size, and high TNM stage according to our study." (PMID 22929401, 2012). "Lung cancer tissues exhibited higher expression levels of Hsp90-beta and annexin A1 than the normal tissues (p < 0.05), and the expression levels of the markers were significantly associated with the pathological grade and lymphatic invasion of lung cancer (p < 0.05)." (PMID 22929401, 2012). "Thus far, research on Hsp90-beta and annexin A1 expression patterns in lung cancer are confined to the basic research in vitro, and the expression status of lung cancer patients is rarely studied." (PMID 22929401, 2012). "In the current study, we identified the upregulation of Hsp90-beta and annexin A1 in lung cancer cells, and we further investigated the significance of this upregulation in lung cancer and the potential use of Hsp90-beta and annexin A1 as clinical markers for lung cancer." (PMID 22929401, 2012). "Kaplan–Meier plots were generated using ANXA1 RNA-seq gene expression and probability of survival data from The Cancer Genome Atlas (TCGA) to evaluate any link between ANXA1 RNA expression and patient survival probability in breast, pancreatic, ovarian, colorectal and lung cancer." (PMID 38200229, 2024). "The association between ANXA1 and EGFR in lung cancer cells was observed in our study, and our study results may provide another mechanism in which ANXA1 promotes the metastasis of lung cancer cells through the modulation of the EGFR pathway." (PMID 34439260, 2021). "In the same manner, higher expression levels of ANXA1 were detected in sera obtained from patients with lung-cancer compared with matched high-risk controls, who did not go on to develop lung cancer, thus suggesting the potential for ANXA1 to act as a biomarker for cancer diagnosis and prognosis." (PMID 29614751, 2018). "However, the effect of Hsp90-beta and annexin A1 in lung cancer remains poorly understood." (PMID 22929401, 2012). "In lung cancer cell lines with non-small cell histologies (H1299 and A549), ANXA1 overexpression inhibited EMT, whereas ANXA1 silencing resulted in increased ß-catenin expression." (PMID 40361334, 2025). "One study identified twelve proteins, such as members of the annexin family (annexin A1, A2, A3, A5, A6, A11), along with PR-OM1, MUC1, BPIFA1, CRNN, MUC5B and IQGAP, which showed significant differences between lung cancer patients and healthy individuals." (PMID 40575159, 2025). "Although the exact mechanisms of ANXA1 involvement in angiogenesis are not yet fully understood, its expression is increased in various malignancies, including CRC, melanoma, and lung cancer." (PMID 41283264, 2025). "ANXA1 expression has been reported to correlate with the development of hepatocellular carcinoma (HCC), colorectal cancer (CRC), lung cancer, pancreatic cancer, melanoma and skin cancer." (PMID 38893148, 2024). "A recent study showed that ANXA1 expression was upregulated in patients with small cell lung cancer bone metastases and promoted bone metastasis of small cell lung cancer cells in mice, suggesting that ANXA1 may be a potential biomarker for lung cancer bone metastasis." (PMID 36988561, 2023). "Further study showed that the knockdown of ANXA1 inhibited the phosphorylation of EGFR and down-stream Akt pathways and promoted apoptosis in lung cancer cells treated with Osimertinib." (PMID 34439260, 2021). "Annexin A1 (ANXA1) has been reported to promote tumor growth and resistance to chemotherapy drugs in lung cancer cells." (PMID 34439260, 2021).